RNU6-395P (RNA, U6 small nuclear 395, pseudogene)
Gene: Small nuclear RNA gene on chromosome 2 (127,845,236 to 127,845,341, forward strand). Ensembl gene ENSG00000202532.
Homologues: Orthologues: chimpanzee U6 (97% identical), mouse Gm24762 (76% identical). Paralogues in human: RNU6-1331P (82% identical), RNU6-386P (82% identical), RNU6-743P (82% identical), RNU6-1091P (81% identical), RNU6-1145P (81% identical), RNU6-11P (81% identical), RNU6-1329P (81% identical), RNU6-15P (81% identical), RNU6-188P (81% identical), RNU6-37P (81% identical), RNU6-38P (81% identical), RNU6-477P (81% identical), and 1287 more.